ACE (angiotensin I converting enzyme)
Diseases named in the same sentence as ACE in open-access papers (continued):
Sharing a sentence is not in itself a finding about the gene and the disease.
Hypertension (continued). "Second, the renin-angiotensin II-aldosterone axis has been traditionally recognized as a key regulator of blood pressure in the development of hypertension, with AngII levels regulated by ACE." (PMID 33580165, 2021). "In subgroup analyses, increased risk for ESKD in VIM quartile 4 versus quartile 1–3 was more evident in individuals aged 40–64 years, with a prescription history of ACE inhibitors or ARBs, hypertension, and dyslipidemia." (PMID 34945244, 2021). "This review aimed to assess the efficacy and safety of once- versus twice-daily administration of angiotensin-converting enzyme (ACE) inhibitors for the management of hypertension." (PMID 34567875, 2021). "The predictive value of high FGV on the incident ESKD was more prominent in patients with young age; hypertension; dyslipidemia; a long duration of diabetes; and who were treated with ACE inhibitors or ARBs, metformin, sulfonylurea, AGI, and insulin." (PMID 34945244, 2021). "Several studies have demonstrated the role of ACE inhibitors in increasing the number and function of EPCs in patients with hypertension and stable CAD13,15." (PMID 34707860, 2021). "Enzymes that are drug targets for NCDs include lipase (obesity), α-amylase and α-glucosidase (diabetes), angiotensin-converting enzyme (ACE) (hypertension) as well as acetylcholinesterase (AChE), butyrylcholinesterase (BChE) and β-secretase (BACE-1) (AD)." (PMID 34451608, 2021). "We found that genes related to hypertension—such as ACE, ANG, CAD, BMPR2, and other genes—were also significantly expressed in ascending aortic dissection tissue reported in the literature." (PMID 34262602, 2021). "The conventional medications used so far for the treatment of hypertension mainly include calcium channel blockers (CCBs), angiotensin-converting enzyme (ACE) blockers, ARBs, and beta-adrenergic blocking agents (β-blockers)." (PMID 34198801, 2021). "Within this geriatric population, 82% of residents presented with pre-existing hypertension treated with ACE inhibitors or ARBs in 30% and 20%, respectively." (PMID 33837912, 2021). "Xerostomia has been associated to an array of chronic pathologies and medications such as hypertension and Angiotensin-converting enzyme (ACE) inhibitor treatment, diuretics, and medication for psychological disorders such as anxiety or depression." (PMID 34023839, 2021). "Many studies report bioactive peptides derived from bean proteins with potential for the treatment of hypertension, due to its ability to inhibit ACE activity (21,)." (PMID 33886808, 2021). "Angiotensin-converting enzyme inhibitors (ACE-i) are commonly used medications to treat hypertension and congestive heart failure." (PMID 33898114, 2021). "Afterward, the B,N-CQDs were used as fluorescent probes for the detection of the drug captopril, an angiotensin-converting enzyme (ACE) inhibitor used for the treatment of hypertension, based on an inner filter effect and a static quenching effect." (PMID 33804394, 2021). "Many chemically synthesized ACE inhibitors such as captopril, lisinopril, and enalapril, have been widely used to control hypertension." (PMID 35011025, 2021). "As for outcome, of 20 women (4.6%) with CVD, 17 had hypertension treated with ACE inhibitors (n = 10), beta-blockers (n = 10), and diuretics (n = 3, in combination with the others)." (PMID 34078945, 2021). "Orally administered STS improves systolic function, and ameliorates hypertension, left ventricular hypertrophy, fibrosis and systemic oxidative stress, all to the same extent as ACE inhibition." (PMID 33935760, 2021). "Among patients diagnosed with hypertension, the use of ACE inhibitors (ACEi) was highest in W1 (type 1 diabetes, 65.0%; type 2 diabetes, 55.7%) but had fallen by W7 (type 1 diabetes, 55.9%; type 2 diabetes, 41.1%)." (PMID 33594476, 2021). "Our data showed that DMB protected hypertension is associated with the restoration of expression of AGT and ACE induced by TCDD." (PMID 34578924, 2021).
Hypertension (continued). "That association remained statistically significant after adjustment for age, gender, hypertension, angina pectoris class, nitrate, ACE inhibitors, and diuretics use." (PMID 34886173, 2021). "Currently, angiotensin-converting enzyme (ACE) inhibitors are targeted as an alternative treatment of hypertension via the renin-angiotensin-aldosterone (RAAS) hormonal cascade." (PMID 33670795, 2021). "And ACE inhibitors are a well-established approved class of drugs for the treatment of hypertension, heart failure and diabetes mellitus." (PMID 33417599, 2021). "The effect of ‘Benifuki’ tea on human hypertension is mainly the result of the strong inhibitory effect of EGCG3”Me on angiotensin I-converting enzyme activity." (PMID 34659317, 2021). "Adult rat offspring of diabetic mothers developed hypertension coinciding with increased angiotensin-converting enzyme (ACE) activity." (PMID 34072634, 2021). "ACE inhibitors can reduce angiotensin II, leading to vasodilation and a subsequent decrease in blood pressure (i.e., vaso-protection against hypertension)." (PMID 34947975, 2021). "Patients with hypertension received angiotensin-converting enzyme (ACE) inhibitors (ramipril, enalapril)." (PMID 34574014, 2021). "We provide an overview of ACE and inhibitors that link a wide variety of age-related comorbidities from hypertension to AD to aging." (PMID 34947975, 2021). "In the presence of arterial hypertension, the administration of an angiotensin-converting enzyme (ACE) inhibitor or an angiotensin (AT)-II receptor blocker is recommended." (PMID 34091756, 2021). "In this study, there were 19 patients using at least one ARB or ACE inhibitor for treatment of hypertension." (PMID 33992075, 2021). "The renin–angiotensin–aldosterone system (RAAS) hormonal cascade is one of the most significant pathways to preserve hemodynamic stability, with ACE as the key enzyme in this mechanism to control hypertension." (PMID 33429899, 2021). "This last receptor is probably up-regulated due to the common treatment of type 1 and type 2 diabetes with ACE inhibitors and ARBs, also used for hypertension." (PMID 33729332, 2021). "Of the patients older than 70 years analysed, 76% had hypertension and 56.5% were preoperatively treated with ACE inhibitors." (PMID 33113315, 2021). "Both ACE inhibitors and ARBs are commonly used in patients with hypertension, heart failure, coronary artery disease, diabetes and chronic kidney disease (CKD)." (PMID 33613842, 2021). "ACE inhibitors are commonly prescribed and widely used in clinical practice as standard therapy, in mono or polytherapy, for the management of hypertension and heart failure." (PMID 33919991, 2021). "Synthetic ACE inhibitors (ACEIs), such as captopril, enalapril, lisinopril, alacepril, and ramipril, are widely used in the management of hypertension." (PMID 34940650, 2021). "ACE2 is also found lining the cells of the pancreatic islets, hence patients with diabetes and hypertension can be treated with ACE inhibitors (ACEi)." (PMID 33842709, 2021). "For example, elderly patients with hypertension taking ACE inhibitor drugs have a significantly slower decline in muscle strength and mobility than the ones taking other antihypertensive drugs." (PMID 34553120, 2021). "Duration of hypertension was slightly longer for users of ACE inhibitors than CCBs (9.8 years vs 8.6 years, respectively)." (PMID 33722197, 2021). "In the severe group, a significantly higher number of patients suffered from hypertension, diabetes and were using ACE inhibitors, compared to mild and moderate groups (p < 0.001, p < 0.001, p < 0.001, respectively)." (PMID 34150833, 2021). "This is particularly true in patients receiving ACE inhibitors to control hypertension, a treatment that is becoming more widespread." (PMID 35011651, 2021). "In patients with CAE with concomitant hypertension, ACE inhibitors should be the first line of management due to their evident role in pathogenesis." (PMID 34660041, 2021).
Hypertension (continued). "Studies on rats with spontaneous hypertension showed that the hydrolysate obtained from blue mussel meat has ACE inhibitory activity." (PMID 34084140, 2021). "Food-derived ACE-inhibitory peptides are promising components for the prevention and treatment of hypertension." (PMID 34945499, 2021). "Overall, 25% were receiving beta-blockers, mostly for palpitation or chest pain, and 22% were receiving angiotensin-converting enzyme (ACE) inhibitors or angiotensin receptor blockers (ARBs), primarily for hypertension." (PMID 34274268, 2021). "ACE inhibitors are used as a first-line medication to be prescribed to treat hypertension, chronic kidney disease, and heart failure, among others." (PMID 34947975, 2021). "Isofraxidin has also shown anti-hypertension effects via inhibiting the activity of angiotensin I converting enzyme (ACE)." (PMID 33477910, 2021). "ACE- inhibitors, angiotensin receptor blockers, beta-blockers, Ca- antagonists are recommended as first-line monotherapy for hypertension." (PMID 34567170, 2021). "Among the patients tested for COVID-19, 75,527 (32.2%) had a history of hypertension; of these, 1911(2.5%) were COVID-19-positive and 13,116 (17.4%) patients took ACE inhibitors or ARBs." (PMID 33588797, 2021). "The bioinformatics analysis by the BIOPEP-UWM database showed possible effects to control hypertension through ACE and renin inhibition." (PMID 34681387, 2021). "The inhibition of the angiotensin-converting enzyme (ACE) by phenolic compounds has been used to treat hypertension." (PMID 35011465, 2021). "Inhibition of ACE is a widely used strategy for the treatment of hypertension, so the food and pharmaceutical industries have an ongoing interest in new sources of ACE inhibitors with antihypertensive activity." (PMID 34711215, 2021). "The patients were under treatment for chronic kidney disease, diabetes and hypertension including angiotensin-converting enzyme (ACE) inhibitors and angiotensin receptor blockers (ARB) as needed." (PMID 34946835, 2021). "In a clinical study, hypertension status was also confirmed as an independent confounding determinant of the ACE to ACE2 ratio, leading to the relative downregulation of ACE2." (PMID 34938578, 2021). "In the in silico study, the affinity of Criollo cocoa peptides for hypertension-related molecular targets ACE, renin, and AT1-R has been demonstrated." (PMID 34681387, 2021). "Increased ACE1/ACE2 ratio and in fact a shift toward ACE/Ang II/AT1R leads to the progression of different complex diseases such as hypertension, atherosclerosis, heart or kidney failure, and severe acute respiratory distress." (PMID 34867452, 2021). "Captopril is an angiotensin-converting enzyme (ACE) inhibitor that is widely prescribed as a drug for the treatment of hypertension." (PMID 33498198, 2021). "An ACE inhibitor or sartan was indicated in 12 (48%) of our patients due to concomitant hypertension during follow-up." (PMID 34830647, 2021). "ACE as an angiotensin-converting enzyme has been used as a drug target to control hypertension and related complications." (PMID 34947975, 2021). "As a result, for the prevention and treatment of hypertension, it is vital to look for natural, safe, and more effective ACE-inhibitory medicines as alternatives." (PMID 34564142, 2021). "Many studies have shown that food sources rich in polyphenols are powerful for preventing and treating hypertension, specifically through ACE inhibition." (PMID 35011465, 2021). "Agents that stimulate Mas, the end receptor of the ACE-2 product Ang1-7, have been studied in preclinical studies, especially for treatment of hypertension." (PMID 34414260, 2021). "Angiotensin-converting enzyme (ACE) is a major target for hypertension in the renin–angiotensin-aldosterone system." (PMID 34829637, 2021). "ACE is involved in the conversion of Ang I to Ang II, and increases Ang II as a potent vasoconstrictor, leading to hypertension." (PMID 33921823, 2021).
Hypertension (continued). "A retrospective study carried out by Corey and colleagues suggested a reduction in liver fibrosis and necroinflammation in patients with chronic hepatitis C who received ACE inhibitors and ARBs as a treatment for hypertension." (PMID 33670126, 2021). "Though we were not able to collect information on comorbidities and medications, most diabetics in Lithuania are generally treated for arterial hypertension with ACE inhibitors." (PMID 34946325, 2021). "Interrupting ACE inhibitors and ARBs treatments in asymptomatic and stable patients with heart failure, kidney disease, diabetes or hypertension will disrupt clinical care and strongly require additional medical visits." (PMID 34925477, 2021). "As the alternative for ACE inhibitors, ARBs are often recommended as the first-choice drugs in treating hypertension." (PMID 33477530, 2021). "For this reason, synthetic ACE inhibitors, such as captopril and enalapril, are mainly used to treat hypertension." (PMID 34829637, 2021). "A number of clinically approved drugs indirectly reduce plasma PAI-1; these include insulin sensitizing agents for management of T2DM, such as metformin, and ACE inhibitors (used to treat hypertension)." (PMID 33937363, 2021). "Patients with hypertension and diabetes treated with ACE inhibitors show increased expression of ACE2." (PMID 34063160, 2021). "Hypertension is usually controlled with ACE inhibitors and angiotensin II type-I receptor blockers (ARBs), drugs that up-regulate ACE2, probably increasing opportunities for viral infection." (PMID 33729332, 2021). "Most guidelines recommend the use of angiotensin-converting enzyme (ACE) inhibitors as the first-line antihypertensive therapy for the treatment of hypertension in patients with chronic kidney disease (CKD)." (PMID 33766008, 2021). "In fact, we found that chronic treatment with HDR-2 significantly reduced ACE activities in plasma and target organs for hypertension, such as lung tissue." (PMID 34711215, 2021). "Although angiotensin-converting enzyme (ACE) inhibitors have been extensively used for controlling hypertension, angioedema is one of the critical side effects." (PMID 33398469, 2021). "MiR-27b and miR-145 attenuate angiotensin converting enzyme-1 (ACE-1) expression, but these miRNAs are downregulated in hypertension, increasing ACE-1 expression." (PMID 34944415, 2021). "The original synthesis of ACE inhibitors involved the compounds which are obtained from the venom of pit vipers, but today, synthetic ACE inhibitors are widely used as a means of controlling hypertension in human patients." (PMID 34473745, 2021). "Previous studies have demonstrated that SS rats are considered a low renin model of hypertension and are resistant to ACE inhibitors." (PMID 34975523, 2021). "Hypertension can be controlled via inhibition of angiotensin-converting enzyme (ACE), the key enzyme in renin-angiotensin-aldosterone (RAAS) hormonal cascade." (PMID 33670795, 2021). "The ACE is one of the key factors for cardiovascular disease, and the inhibition of ACE activity is related to the prevention of high blood pressure." (PMID 33916201, 2021). "In one study, anthocyanins reduced blood pressure by a similar magnitude as captopril, an angiotensin-converting enzyme (ACE) inhibitor used to treat high blood pressure." (PMID 33494165, 2021). "Treatment with the ACE inhibitor ramipril decreased thrombin generation, as compared to placebo, in essential hypertension." (PMID 34220496, 2021). "Currently, several peptide drugs, namely, captopril, lisinopril, and enalapril, are used as ACE inhibitors for the management of high blood pressure." (PMID 34234885, 2021). "In essential hypertension, there is a defect in the ACE/ACE2 balance, and this is more common in obese patients." (PMID 34650947, 2021). "Essential hypertension, for example, is related to some genetic mutations in RAS components, such as the AT1R gene, and to angiotensinogen (AGT) M235T and ACE I/D polymorphisms." (PMID 34834033, 2021).
Hypertension (continued). "Captopril is an inhibitor of angiotensin converting enzyme (ACE), which is commonly used to low blood pressure in patients with high blood pressure." (PMID 34607529, 2021). "Trandolapril and Ramipril are synthetic ACE inhibitor drugs that control high blood pressure and congestive heart failure." (PMID 34351937, 2021). "ACE inhibitors, ARB, and BB were widely used as monotherapies in both studies; ARB (24.2% of all with treated hypertension) was the most commonly used therapy in Tromsø 7, while ACE (15.5%) was the most common in KYH." (PMID 32169049, 2020). "Both peripheral and brain renin-angiotensin systems play a fundamental role in hypertension, hence ACE inhibitors are currently used to treat it." (PMID 32470081, 2020). "Several mechanisms through which ROS induce hypertension include decreasing nitric oxide bioavailability, up-regulating ACE activity, and activating angiotensin II type 1 (AT1) receptor." (PMID 32325920, 2020). "In depth, among the 34 patients with arterial hypertension, 8 (23.5%) were on ACE inhibitors and 11 (32%) on angiotensin receptor blockers." (PMID 33585520, 2020). "The angiotensin-converting enzyme (ACE) plays an important role in the development of hypertension by converting angiotensin I to angiotensin II." (PMID 32526850, 2020). "Angiotensin-converting enzyme (ACE) inhibitors are predominately administered to the patients with hypertension because of their decreasing effect on vascular resistance and blood pressure without considering cardiac condition." (PMID 32765804, 2020). "Captopril is the first angiotensin I-converting enzyme inhibitor widely used for the treatment of hypertension." (PMID 32784691, 2020). "Inhibition of the ACE is a widely used strategy for the treatment of hypertension so the food and pharmaceutical industries are always interested in new sources of ACE inhibitors with antihypertensive activity." (PMID 31968696, 2020). "Angiotensin Converting Enzyme (ACE) inhibitors are widely used as a first line medication for the treatment of hypertension in the UK, although their use was suggested in early reports to increase the risk associated with SARS-CoV-2 infection." (PMID 32873147, 2020). "Ang II inhibitors such as ACE inhibitors and ARBs have developed as anti-hypertensive agents and used in patients with hypertension." (PMID 31655853, 2020). "Two patients experienced proteinuria and arterial hypertension (grade III adverse events) requiring medication with angiotensin-converting enzyme (ACE) inhibitors and one received a beta blocker in addition during the first 6 months." (PMID 32548671, 2020). "Her past medical history includes hypertension well controlled by angiotensin-converting enzyme (ACE) inhibitors, asthma aggravated by tobacco smoking, and surgical treatment of endometriosis." (PMID 32019608, 2020). "Based on these results, sesame protein can be a promising ACE inhibitor in the prevention and treatment of hypertension." (PMID 32033479, 2020). "The molecular mechanism of these peptides in hypertension includes the inhibition of angiotensin I-converting enzyme." (PMID 33348926, 2020). "Consistent predictors of post-AMI IS included prior IS, CABG surgery, prior atrial fibrillation, prior hemorrhagic stroke, heart failure during hospitalization, older age, diabetes mellitus, hypertension, and use of ACE inhibitors at discharge." (PMID 32123285, 2020). "A controversial aspect of the management of COVID-19 has been the use, in some patients with hypertension, of ACE inhibitors (ACEI) and angiotensin receptor blockers (ARB)." (PMID 32868984, 2020). "Medications such as ACE inhibitors and angiotensin II receptor antagonists conventionally prescribed for hypertension need to be discontinued upon pregnancy diagnosis, due to the deleterious fetal effects." (PMID 32577117, 2020).